FAHD2B (fumarylacetoacetate hydrolase domain containing 2B)
Description:
Tautomerase that converts enol-oxaloacetate, a strong inhibitor of succinate dehydrogenase, to the physiological keto form of oxaloacetate. It is thereby required to maximize aerobic respiration efficiency by preventing succinate dehydrogenase inhibition.
Synonyms: DKFZp434N062
Tractability: PROTAC: ubiquitination databases record sites on it.
Gene: Protein-coding gene on chromosome 2 (97,082,040 to 97,094,903, reverse strand). Ensembl gene ENSG00000144199.
Subcellular location: Mitochondrion
Gene Ontology:
Molecular function: oxaloacetate tautomerase activity; protein binding; catalytic activity
Biological process: oxaloacetate metabolic process
Cellular component: mitochondrion
Genetic constraint (gnomAD): Loss-of-function variants: 25 observed, 31.75 expected, observed/expected ratio (o/e) 0.79, 90% interval 0.57 to 1.1. The synonymous counts are far from expectation, so gnomAD's model fits this gene poorly and the ratio says little. Missense variants: 272 observed, 378.91 expected, observed/expected ratio (o/e) 0.72, 90% interval 0.65 to 0.79. Synonymous variants: 108 observed, 145.93 expected, observed/expected ratio (o/e) 0.74, 90% interval 0.63 to 0.87.
Homologues: Orthologues: zebrafish fahd2a (61% identical), Drosophila melanogaster CG6028 (40% identical), Drosophila melanogaster CG11251 (36% identical). Paralogues in human: FAHD2A (98% identical), FAH (25% identical), FAHD1 (25% identical).
Diseases named in the same sentence as FAHD2B in open-access papers:
FAHD2B is named in the same sentence as 2 diseases in open-access papers, as found by Europe PMC text mining. Sharing a sentence is not in itself a finding about the gene and the disease. The quoted sentences say what the papers report.
bipolar disorder (1 paper, 2021). A disorder of the brain that causes unusual shifts in mood, energy, activity levels and the ability to carry out day-to-day tasks. "Also, only CEWAS found FAHD2B, HDAC5, MBTD1, NME2, and XPNPEP3 for bipolar disorder." (PMID 34807913, 2021).
cancer (1 paper, 2021). A tumor composed of atypical neoplastic, often pleomorphic cells that invade other tissues. "ANKRD36 has been reported to be coexpressing and interacting with other genes on locus 2q11.2, including ANKRD36C, ITPRIPL1, FAHD2B, FAM178B and CNNM3, which shows that ANKRD36 is involved in some important biological networks associated with cancers." (PMID 34827175, 2021).